LITAF (lipopolysaccharide induced TNF factor)
Diseases named in the same sentence as LITAF in open-access papers (continued):
Sharing a sentence is not in itself a finding about the gene and the disease.
Crohn disease (1 paper, 2013). A gastrointestinal disorder characterized by chronic inflammation involving all layers of the intestinal wall, noncaseating granulomas affecting the intestinal wall and regional lymph nodes, and transmural fibrosis. "Locally elevated LITAF protein was reported in Crohn's disease (CD) and ulcerative colitis (UC), two major TNF-mediated inflammatory bowel diseases (IBD)." (PMID 23414097, 2013). "LITAF has been demonstrated to play an important role in rheumatoid arthritis, Crohn's disease, innate immune dysregulation in the central nervous system and inflammatory changes in mesenteric fat linked to metabolic syndrome in obesity and insulin resistance." (PMID 23414097, 2013).
diabetes (1 paper, 2018). "The upregulation of certain mRNA isoforms of the ITGA5, TIMP1, ANXA2 and LITAF genes in HIGH pigs is relevant because these four genes have been implicated in human obesity and diabetes." (PMID 29444639, 2018).
diffuse large B-cell lymphoma (1 paper, 2016). "Recent studies have showed, both mRNA and protein expression of LITAF are significantly down-regulated in germinal centre (GC) B-cell-like diffuse large B-cell lymphoma (GCB-DLBCL), which display constitutively high BCL6 expression." (PMID 27764808, 2016).
epilepsy (1 paper, 2025). A brain disorder characterized by episodes of abnormally increased neuronal discharge resulting in transient episodes of sensory or motor neurological dysfunction, or psychic dysfunction. "Targeting LITAF and its downstream mechanisms may offer a promising therapeutic strategy for managing epilepsy." (PMID 39764629, 2025). "Our findings demonstrate that LITAF regulates MCL‐1 ubiquitination, significantly impacting mitochondrial autophagy and contributing to neuronal damage in epilepsy." (PMID 39764629, 2025).
fatty liver disease (1 paper, 2023). A reversible condition wherein large vacuoles of triglyceride fat accumulate in liver cells via the process of steatosis. "Lipopolysacharide-induced TNF factor (LITAF) connects inflammation to fatty liver disease, and its expression correlates with histological grades of fibrosis." (PMID 36674967, 2023).
glioblastoma (1 paper, 2025). The most malignant astrocytic tumor (WHO grade IV). "To verify the impact of three genes on the prognosis of glioblastoma patients, we analyzed the TCGA-GBM database and found that high expression of LITAF and OSMR significantly shortened patient overall survival, while high expression of TCF12 significantly extended patient overall survival." (PMID 40859405, 2025).
Hyperkeratosis (1 paper, 2021). Hyperkeratosis is a histopathological term defining a thickened stratum corneum and may be present in many different skin conditions, with many possible overlaps. "The overlapping DEGs included genes associated with hyperkeratosis (upregulated LCE3E and TMEM45A), wound healing (upregulated KRT17, IL36G, TNC, and TGFBI), barrier defects (downregulated FRAS1 and BCL11A), and response to infection (upregulated IL36G, ADAP2, DFNA5, RFTN1, LITAF, and TMEM173)." (PMID 34506598, 2021).
Insulin resistance (1 paper, 2024). Increased resistance towards insulin, that is, diminished effectiveness of insulin in reducing blood glucose levels. "TNF-alpha is an adipokine known to negatively regulate adipogenesis and induce insulin resistance, which suggest that LITAF is an important upstream mediator of adipogenesis." (PMID 38991381, 2024).
liver disorder (1 paper, 2015). A disease involving the liver. "Despite plentiful evidence regarding LITAF regulation in macrophage populations, to date no studies have clarified LITAF involvement in the pro-inflammatory and pro-fibrogenic pathways related to liver disorders." (PMID 26573228, 2015).
lymph node metastasis (1 paper, 2023). "Interestingly, we also noticed that LITAF expression was significantly increased in PDAC patients with lymph node metastasis compared with those without lymph node metastasis." (PMID 37612267, 2023).
mediastinal lymphoma (1 paper, 2016). "For example, LITAF is silenced by homologous deletion in primary mediastinal lymphoma and by promoter hypermethylation in germinal center lymphoma." (PMID 26717043, 2016).
neuropathy (1 paper, 2021). A disorder affecting the nervous system that manifests with pain, tingling, numbness, and/or muscle weakness. "Charcot-Marie-Tooth 1C (CMT1C) is a rare form of dominantly inherited CMT1 neuropathy caused by a mutated gene encoding lipopolysaccharide-induced tumour necrosis alpha factor (LITAF)." (PMID 34311727, 2021).
Obesity (1 paper, 2018). Accumulation of substantial excess body fat. "The increased levels of specific ITGA5, LITAF, TIMP1 and ANXA2 mRNA isoforms in HIGH pigs is consistent with reports indicating that the overexpression of these four genes is associated with obesity and metabolic disorders in humans." (PMID 29444639, 2018).
pancreatic carcinoma (1 paper, 2018). "Additionally, there was a significant inverse association between LITAF mRNA expression and methylation status of LITAF promoter in 25 paired pancreatic tumor tissues (p < 0.001)." (PMID 29423035, 2018). "However, the relationship between LITAF somatic mutations and its aberrant expression is unclear, and the LITAF function in pancreatic cancer is unknown." (PMID 29423035, 2018). "Our epigenetic data show that demethylation of the LITAF promoter inhibits cell proliferation, survival and cell cycle of pancreatic carcinoma cells." (PMID 29423035, 2018). "The decreased LITAF expression correlated with LITAF promoter hypermethylation in pancreatic cancer cells and tissues." (PMID 29423035, 2018). "Together, our results indicate that LITAF functions as a tumor suppressor in pancreatic cancer cells." (PMID 29423035, 2018). "Here, we investigated the biological function of LITAF through the epigenetic analysis of pancreatic cancer cells and tissues." (PMID 29423035, 2018). "To understand the molecular mechanisms regulating LITAF transcription in pancreatic cancer, we first analyzed LITAF mRNA expression in four pancreatic cancer cell lines (BxPC-3, AsPC-1, CFPAC-1 and PANC-1) by RT-qPCR." (PMID 29423035, 2018). "In order to evaluate the LITAF function in regulating tumorigenesis of pancreatic cancer cells, cell proliferation, apoptosis, and cell cycle were analyzed." (PMID 29423035, 2018). "Similarly to studies in other solid cancers, we found that the expression of LITAF was downregulated in most of pancreatic cancer cases (76%, 19/25); most of them were pancreatic ductal adenocarcinoma." (PMID 29423035, 2018). "Here, we analyzed the biological function of LITAF in pancreatic cancer." (PMID 29423035, 2018). "Our results suggest that the methylation status of the LITAF promoter may be considered as a candidate biomarker for molecular therapy of pancreatic cancer." (PMID 29423035, 2018). "In this study, we investigated the LITAF function in pancreatic cancer." (PMID 29423035, 2018). "Our results indicate that LITAF functions as a tumor suppressor in pancreatic cancer, and may serve as potential biomarker for early diagnosis of pancreatic cancer." (PMID 29423035, 2018). "Whether LITAF might serve as a target gene in early diagnosis of pancreatic cancer needs further analysis in patients with early-stage pancreatic cancer." (PMID 29423035, 2018). "Importantly, LITAF demethylation suppressed proliferation and cell cycle progression, and enhanced apoptosis of pancreatic cancer cells." (PMID 29423035, 2018). "In this study, we have investigated the LITAF function in pancreatic cancer to test whether it could serve as a potential biomarkers for early diagnosis and target therapy." (PMID 29423035, 2018). "Our results demonstrate that the methylation degree of LITAF promoter regulates the LITAF expression, suggest that the LITAF promoter methylation may represent one of the mechanisms responsible for the pathogenesis of pancreatic cancer." (PMID 29423035, 2018). "Together, our results indicate that LITAF functions as a tumor suppressor gene in pancreatic cancer cells, and might serve as a novel biomarker for early diagnosis of pancreatic cancer." (PMID 29423035, 2018). "To investigate if promoter methylation might be responsible for the downregulation of LITAF, we examined the methylation status of the promoter region of LITAF by using MSP and BSP in the four pancreatic carcinoma cell lines and 25 paired pancreatic cancer samples." (PMID 29423035, 2018). "Interestingly however, we found that the expression of LITAF mRNA was actually increased in 6 pancreatic cancer cases (24%, 6/25) compared with their paired non-tumor tissues." (PMID 29423035, 2018).
pancreatic carcinoma (continued). "In addition, in our epigenetic study of the LITAF promoter in pancreatic cancer cells and tissues, we noticed not all of pancreatic cancer cases and cells had the same reaction to aberrant methylation of LITAF promoter, indicating existence of different molecular subtypes." (PMID 29423035, 2018).
polyneuropathy (1 paper, 2013). A disease or disorder affecting more than one nerve. "Genetic testing was performed according to polyneuropathy type; demyelinating/mixed: PMP22 duplication, MPZ, EGR2, LITAF, NEFL, PMP22, GJB1, axonal: MFN2, MPZ, NEFL, and GJB1." (PMID 24053775, 2013).
primary progressive multiple sclerosis (1 paper, 2024). A multiple sclerosis that is characterized by steady worsening of neurologic functioning, without any distinct relapses or periods of remission. "The coexistence of primary progressive multiple sclerosis (PPMS) and CMT1C disease may not result from the presence of the mutation in the LITAF gene, but the role of mutated LITAF in inflammation (PPMS) cannot be definitively excluded." (PMID 39795872, 2024).
Ventricular arrhythmia (1 paper, 2020). "The data provided in this study and the evidence of its complex role in regulating multiple ion currents make LITAF an interesting target for innovative strategies in the prevention and treatment of ventricular arrhythmias, not least those associated with reduced Nav1.5 function and INa." (PMID 33093176, 2020).
tumor (23 papers, 2013 to 2026). "Moreover, REEP6 might also regulate LITAF for inducing cancer growth/invasion or switching tumor associated-inflammation." (PMID 37238941, 2023). "In this study, we found that Bag3 and LITAF are key contributors to tumor macrophage infiltration which is mediated by the CSF1 pathway." (PMID 36077705, 2022). "Considered as tumor suppressor in several cancer types, LITAF was also shown to be involved in immune response and autophagy." (PMID 34696794, 2021). "LITAF has previously been described as a tumor suppressor due to its ability to decrease proliferation in vitro and decrease tumor growth in an in vivo model." (PMID 29845714, 2018). "LITAF mRNA levels were downregulated in 19 out of the 25 cases (76%) compared with their adjacent non-tumor tissues (p < 0.05)." (PMID 29423035, 2018). "LITAF is a tumor suppressor that was previously reported to physically interact with ITCH and induce the relocation of ITCH to the lysosomes, likely interfering with ITCH function." (PMID 30285739, 2018). "Lipopolysaccharide-induced tumor necrosis factor-α factor (LITAF) has been recently proposed as a potential tumor suppressor gene in several types of cancer." (PMID 29423035, 2018). "It is possible the tumor suppressive function of LITAF is mediated by its transcriptional activity and its effect on autophagy." (PMID 26717043, 2016). "Our previous study has identified LITAF as a downstream effector of AMPK in regulation of tumor cell growth; however, the mechanism by which it mediates the tumor suppressive function remains to be determined." (PMID 26717043, 2016). "A tumor suppressor role for LITAF has also been reported, and this role invites further study in PMBL." (PMID 26599546, 2015). "In tumor-bearing mice, Lipopolysaccharide-induced tumor necrosis factor alpha factor (LITAF) acts as a tumor suppressor gene, promoting FOXO-1 expression to inhibit SIRT1, thereby upregulating epithelial marker E-cadherin and downregulating mesenchymal marker N-cadherin." (PMID 40567502, 2025). "We found that LITAF is involved in the regulation of macrophage motility and tumor invasion." (PMID 36077705, 2022). "Indeed, silencing of LITAF significantly suppressed macrophage motility and invasion in vitro, as well as their tumor infiltration in vivo." (PMID 36077705, 2022). "LITAF was identified to be a downstream target of AMPK that inhibited tumor growth." (PMID 36405685, 2022). "Here, we hypothesized that the recruitment of TAMs into the tumor site is regulated by the Hsp70–Bag3 complex via LITAF." (PMID 36077705, 2022). "Interestingly however, we found that LITAF mRNA expression of 6 cases (24%, cases 1, 2, 5, 6, 12 and 16) was actually upregulated compared with their adjacent non-tumor tissues." (PMID 29423035, 2018). "Recently, accumulating evidences have indicated that LITAF may be considered as a tumor suppressor in different malignancies." (PMID 27764808, 2016). "In sum, previous publications by us and others support that LITAF functions as a tumor suppressor." (PMID 26717043, 2016). "The regulatory axis of AMPK–LITAF–TNFSF15 even suggests that LITAF may function as a tumour suppressor." (PMID 23414097, 2013). "Collectively, our recent investigation showed that the up-regulation of VEGF expression by the association of LITAF and STAT6B may play an important role in the inflammatory signalling pathway and benefit tumour development." (PMID 23414097, 2013).
tumor (continued). "Therefore, we investigated the evolutionary history of cancer associated gene sequences across 384 mammalian taxa, to detect signatures of selection across categories of oncogenes (GRB2, FGL2 and CDC42), tumour suppressors (LITAF, Casp8 and BRCA2) and immune genes (IL2, CD274 and B2M)." (PMID 38773187, 2024). "According to the previous research, LITAF may be considered as a tumor suppressor." (PMID 36900319, 2023). "We have shown that LITAF acts as transcriptional factor to activate transcription of TNFSF15, so as to inhibit tumor angiogenesis." (PMID 26717043, 2016). "However, several studies suggest that LITAF may have a tumor suppressive role." (PMID 26717043, 2016). "Collectively, our findings provide a novel apoptotic regulatory pathway in which LITAF, as a transcription factor, inhibits the expression of BCL6, which leads to activation of the intrinsic mitochondrial pathway and tumor apoptosis." (PMID 27764808, 2016). "Targeting genes such as LITAF, OSMR, and TCF12 could selectively disrupt myCAF-driven malignancy while preserving anti-tumor stromal functions." (PMID 40859405, 2025). "Additionally, we found that LITAF participates in transcriptional regulation of TNFSF15, a pro-inflammatory cytokine and also a potent inhibitor of tumor angiogenesis." (PMID 26717043, 2016).
infection (14 papers, 2011 to 2023). The state of being infected such as from the introduction of a foreign agent such as serum, vaccine, antigenic substance or organism. "Taken together, we have identified a putative fish LITAF ortholog, which was a constitutive and inducible immune response gene involved in M. amblycephala innate immunity during the course of a pathogenic infection." (PMID 28212275, 2017). "The relative mRNA expression of interleukin (IL)-6, interferon (IFN)-γ, and lipopolysaccharide-induced tumor necrosis factor alpha factor (LITAF) over the course of the infection was evaluated using the qPCR method." (PMID 28659929, 2017). "In comparison with the S group, expression of IFN-γ was decreased at 3 and 5 days post the infection, while expression of LITAF was decreased on d5 in the SP group." (PMID 28659929, 2017). "In sum, these results indicate that the expression levels of proinflammatory cytokines and chemokines IL-1beta, IL-6, IL-8 and LITAF in CEFs and DEFs showed different patterns following infection with NDVs of different pathogenicities." (PMID 26975566, 2016). "SLIT2, LITAF, PRUNE2 and genes involved in “Integrin signalling” showed altered numbers of TashAT2 motifs and, together with “PI3K/AKT signalling”, integrin signalling genes were significantly enriched by IPA in the Infection Associated-H/S data set." (PMID 35061738, 2022). "In addition, several DEGs, including IL36G, ADAP2, DFNA5, RFTN1, LITAF, and TMEM173, that were commonly upregulated in the partial sets of the epithelium and mucosa are associated with the response to infection." (PMID 34506598, 2021). "SGIV LITAF expression coincided with a reduction of the expression of miR-homoHSV, indicating that SGIV may encode miR-homoHSV to inhibit the levels of SGIV LITAF mRNA at an early stage of infection." (PMID 24312676, 2013). "Significant up-regulation (p < 0.05) of LITAF, IL-6 and IL-8 was also detected in lung and spleen tissues from three-week-old chickens at 24 h of infection with H5N1-tyTR05 or H5N1-tyEng91 HPAI viruses (data not shown), along with abundance of virus matrix gene expression." (PMID 25431115, 2014). "Furthermore, LITAF was not inducible in the sorted leukocytes whilst iNOS was induced in macrophages in response to the infection at 4 DPI." (PMID 22384225, 2012). "In contrast, no significant induction of expression of IL6, LITAF, and cytokine IL10 was detected after infection with the different Salmonella strains." (PMID 31998655, 2019).
cancer (10 papers, 2015 to 2024). A tumor composed of atypical neoplastic, often pleomorphic cells that invade other tissues. "LITAF is a downstream target of AMPK that inhibits cancer cell growth by increasing the expression of TNFSF15 and inhibiting angiogenesis." (PMID 39684426, 2024). "In the same way, the LITAF protein has been proposed as a tumor suppressor frequently downregulated in several cancer types." (PMID 33946771, 2021). "The downregulation of LITAF induces cell growth, inhibits apoptosis, and induces cell migration in cancer cells." (PMID 33946771, 2021). "The downregulation of LITAF induces migration, increased cell viability, and colony formation in cancer cells." (PMID 29423035, 2018). "Altogether, our data for the first time suggest a regulatory axis in cancer cells: AMPK upregulates LITAF, which in turn increases miRNAs, leading to attenuation of Bmi-1 expression." (PMID 26717043, 2016). "In the present study, we attempted to depict the linear relationship of AMPK, LITAF and Bmi-1 in cancer cells." (PMID 26717043, 2016). "To decipher the mechanism by which LITAF regulates growth of cancer cells, we performed miRNA microarray analysis on the A549 cells where LITAF was silenced as compared with the control counterpart containing scrambled shRNA." (PMID 26717043, 2016). "The expression of genes such as LITAF can be a sign of a positive cancer prognosis and survival." (PMID 38773187, 2024). "Another aspect of LITAF function is related to its effect on cancer cells." (PMID 26717043, 2016). "Third, knockdown of LITAF, previously identified as a downstream target of AMPK, upregulated Bmi-1, associated with increased cell viability, colony formation, and migration of cancer cells in vitro." (PMID 26717043, 2016). "Therefore, understanding the fine tuning between apoptosis and lymphomagenesis as exemplified by the presented feedback loop between BCL6 and LITAF may offer hope for cancer diagnosis and therapy." (PMID 27764808, 2016).
metabolic disorders (2 papers, 2018 to 2019). "For example, LITAF overexpression was found to be associated with metabolic disorders in humans, whereas sma-2 was demonstrated be involved in metabolic homeostasis." (PMID 31292921, 2019).